EGFR (epidermal growth factor receptor)
Diseases named in the same sentence as EGFR in open-access papers (continued):
Sharing a sentence is not in itself a finding about the gene and the disease.
breast carcinoma (continued). "In breast cancer, the review discusses the intricate relationship between EGFR expression and therapeutic outcomes, emphasizing the challenges and potential strategies for enhancing EGFR-targeted treatments." (PMID 40560045, 2025). "Many different kinds of cells have the receptor EGFR on their surface, but breast cancer cells have a disproportionately high amount of it." (PMID 41283276, 2025). "The docking estimations were conducted to predict the docking pose of DAMNI against ERα and EGFR, both of which are acknowledged for their significance in breast cancer treatment." (PMID 40929235, 2025). "Overexpression or mutation of the EGFR gene markedly enhances cell growth and proliferation, particularly in NSCLC and breast cancer, making EGFR a well-established and effective therapeutic target for these diseases." (PMID 40806193, 2025). "In summary, our study endorses that the EGFR-mTORC2-RICTOR-AKT-UGCG-Ganglioside circuit regulates tumor progression in luminal breast cancer cells and provides us with an opportunity to intervene at multiple nodes to tame cancer cells." (PMID 40934285, 2025). "For example, lapatinib has been reported to impair HR through the inhibition of the EGFR/PARP complex in breast cancer cells." (PMID 41208896, 2025). "Tyrosine kinases, including HER2 and EGFR, are frequently overexpressed in breast cancers, and their activity is closely tied to tyrosine availability." (PMID 40867327, 2025). "Here, we investigated how ER activation by 17β-estradiol (E2), the most potent form of estrogen, affects the expression or activity of EGFR or EGFR-related genes in ER+ breast cancer cells." (PMID 40422206, 2025). "In breast cancer, inhibitors targeting epidermal growth factor receptor (EGFR), human epidermal growth factor receptor 2 (HER2), and cyclin-dependent kinases (CDKs) have emerged as valuable therapeutic options." (PMID 40243953, 2025). "The encouraging results from our established model support further exploration and potential clinical application of this dual degrader approach, especially in gynecologic and breast cancers where FRα, EGFR/HER2, and PD-L1/VISTA are prevalently expressed." (PMID 41038820, 2025). "In this study, various breast cancer cell lines and endometrial cells were used to analyze different expression levels of multiple target antigens (EGFR, FOLR1, HER2, EpCAM, NG2, ANK3 and CTNNB1) through flow cytometry and fluorescence microscopy." (PMID 40422194, 2025). "Overall, our findings enhance our understanding on the interplay between the EGFR and IGF-IR pathways and underscore the value of 3D models in revealing key biological processes underlying distinct breast cancer phenotypes." (PMID 40867236, 2025). "Upon EGFR-TKI treatment, the level of nuclear EGFR in wild-type EGFR-expressing breast cancer cells increases." (PMID 40560045, 2025). "The Ca2+-activated Cl− channel ANO1 facilitates the progression of breast cancer by triggering the activation of EGFR (epidermal growth factor receptor) and CAMK (calcium/calmodulin-dependent protein kinase) signaling pathways." (PMID 40110186, 2025). "In summary, this gene panel offers a reliable method for estimating the number of breast cancer cells mixed with bone marrow cells, with EGFR and EpCAM standing out as the most promising candidates due to their superior specificity and expression levels." (PMID 40073025, 2025). "Although this off‐target interaction did not solve the problem of therapeutic resistance related to double‐mutated EGFR, it has proved to be beneficial by inhibiting EGFR and HER‐2, a crucial aberrant receptor of other types of tumors such as breast cancer." (PMID 41269051, 2025). "The targeting ability of aptamers was also combined with GSH-responsive polymeric NPs for the enhanced delivery of homoharringtonine to EGFR-overexpressing A549 breast cancer cells." (PMID 39940134, 2025).
breast carcinoma (continued). "By examining triple-negative and luminal A breast cancer subtypes, this research evaluates how the inhibition of the EGFR and IGF-IR pathways—separately and in combination—affects cell behavior and extracellular matrix expression." (PMID 40867236, 2025). "Targeting downstream of EGFR by using Trametinib, a mitogen activated protein kinase kinase (MEK) inhibitor, in MDA-MB-231 breast cancer and MDA-MB-435 melanoma cells causes them to stiffen." (PMID 40498131, 2025). "Panitumumab-[197Hg]Hg-AuNPs exhibited high affinity binding to EGFR on U251-Luc cells with a KD = 1.8 × 10–9 mol/L comparable to [177Lu]Lu-DOTA-panitumumab (1.0 × 10–9 mol/L) binding to EGFR-positive MDA-MB-468 human breast cancer cells." (PMID 40676315, 2025). "EGFR is a receptor tyrosine kinase that promotes the proliferation and invasion of breast cancer by stimulating multiple oncogenic pathways such as Ras-Raf-MEK-ERK, PI3K-AKT-mTOR, and Src-STAT3." (PMID 40454580, 2025). "There is an urgent need to study the functional impact of nuclear EGFR in breast cancer growth, migration, and therapeutic response to EGFR-targeted therapies." (PMID 40560045, 2025). "Studies have reported promising activity of MBZ in combination with EGFR inhibitors, including gefitinib, in both lung and breast cancer models." (PMID 41401147, 2025). "This structure-based analysis provides valuable insights into the potential of natural compounds as inhibitors of EGFR/HER2 in breast cancer therapy." (PMID 40082669, 2025). "The most studied molecular targets in breast cancer drug discovery included epidermal growth factor receptor (EGFR), vascular endothelial growth factor receptor‐2 (VEGFR‐2), cyclin‐dependent kinases (CDKs), tubulin, and hormone receptors (ERα and ERβ)." (PMID 41523619, 2025). "In conclusion, our study defines STARD7 as a candidate that promotes cell proliferation as well as both ERα‐ and EGFR‐dependent signaling cascades in breast cancer." (PMID 40443279, 2025). "Previously, a melittin peptide from A. mellifera was demonstrated to suppress the activation of EGFR in breast cancer cells." (PMID 40141140, 2025). "This discrepancy emphasizes the need to explore the mechanisms responsible for resistance to EGFR-targeted therapies in breast cancer." (PMID 40806193, 2025). "The Ohno group also successfully utilized gene-modified exosomes as biomaterials to deliver miRNA to EGFR-expressing breast cancer." (PMID 40134003, 2025). "Although EGFR overexpression has been reported in all types of breast cancer, it is more frequent in TNBC, where it is found in up to 70% of patients." (PMID 40150035, 2025). "Among these RTKs, the epidermal growth factor receptor (EGFR) and insulin-like growth factor I receptor (IGF-IR) are often associated with breast cancer." (PMID 40867236, 2025). "Morin is a also good therapeutic candidate for the treatment of HER2-overexpressing breast cancer as it induces cell death by inhibiting the HER2/EGFR signaling pathway." (PMID 39831267, 2025). "Using single cell tracing of Crispr/Cas9 modified EGFR to express an EGFR-mVenus fusion protein, we validated the strong reduction of nEGFR in T47D (T47D-mVenus) breast cancer cells treated with cSNX1.3 compared to control cPTD4 treated cells." (PMID 39521886, 2025). "The cross-talk between mesenchymal-epithelial transition factor (c-MET) and epidermal growth factor receptor (EGFR) plays a role in breast cancer (BC) progression and resistance to various targeted therapies." (PMID 41234389, 2025). "We treated ER+ breast cancer cells with lapatinib to inhibit the AREG/EGFR signaling pathway and then completely inhibited E2-induced cell proliferation and S-phase induction." (PMID 40422206, 2025). "It promotes chromosomal instability and metastasis in breast cancer, enhances tumor progression and chemoresistance via Wnt/β-catenin signaling in colorectal cancer, and modulates EGFR signaling in pancreatic cancer." (PMID 41208974, 2025).
breast carcinoma (continued). "EGFR overexpression is often observed in many solid tumors, such as breast cancer, head and neck cancer, NSCLC, renal cancer, ovarian cancer, and colon cancer." (PMID 39780275, 2025). "Clinical trials with the EGFR TKI gefitinib in breast cancer have shown limited clinical responses and a low disease control rate, particularly in triple-negative breast cancer, despite the higher degree of EGFR overexpression in this subtype." (PMID 40560045, 2025). "Tumor-stromal interactions appear to contribute to the intrinsic sensitivity of breast cancer cells to EGFR TKIs, providing an alternative approach to confer EGFR therapy resistance in breast cancer." (PMID 40560045, 2025). "These TSLs were further coated with cetuximab (CET), an antibody targeting epidermal growth factor receptor (EGFR)-expressing breast cancer cells." (PMID 39997849, 2025). "While this pathway represents a large cohort of regulatory genes, we selected the EGFR gene for further study due to its role in bladder cancer and breast cancer cell migration and invasion during metastatic progression." (PMID 40754248, 2025). "expressed that exosomes carrying anti-tumor miRNA against epidermal growth factor receptor (EGFR) can be used to treat breast cancer." (PMID 40475972, 2025). "Background/Objectives: Epidermal growth factor receptor-tyrosine kinase inhibitors (EGFR-TKIs) are a promising therapeutic avenue against mammary cancer." (PMID 41304988, 2025). "Altogether, these results implied that ADAM12 actively reinforces the CSC phenotypes in claudin-low expressing breast carcinoma cells by modulating the EGFR pathway." (PMID 38317965, 2024). "Eventually, strong correlation was detected between the immunostaining levels of anti-ADAM12L and anti-phospho-EGFR in human breast carcinomas using tissue microarrays." (PMID 38317965, 2024). "Five proteins (i.e., EGFR, MAPK3, ESR1, MAPK1, and PTGS2) associated with breast cancer were selected as receptor proteins." (PMID 38794187, 2024). "TGFβ-induced EGFR upregulation in breast cancer cells can be mediated by the canonical SMAD3 and ERK/SP1 signaling pathways." (PMID 39468555, 2024). "The PI3K-Akt signaling pathway, MAPK signaling pathway, pathways in cancer, HIF-1 signaling, and EGFR tyrosine kinase inhibitor resistance stand out as the most relevant among the various breast cancer-related signaling pathways covered by these pathways." (PMID 39057437, 2024). "Several oncogenes are reported to be involved in breast cancer carcinogenesis, including Ras, c-myc, epidermal growth factor receptor (EGFR, erb-B1), and erb-B2 (HER-2/neu)." (PMID 38293453, 2024). "EGFR is overexpressed in a wide variety of solid tumors such as epidermoid carcinomas, lung and liver cancer, malignant gliomas, and breast cancers." (PMID 39435057, 2024). "Studies have shown that genomic alterations in EGFR play an important role in tumor cell growth in breast cancer." (PMID 38892065, 2024). "For instance, SMART-Exos containing monoclonal antibodies CD3 and EGFR can induce cross-linking between T cells and EGFR-positive breast cancer cells." (PMID 38543204, 2024). "For example, it was also shown that subcutaneous administration of PA-MSHA (2.2 × 1010 cells/mL) for 45 days reduces the growth and development of breast cancer with EGFR overexpression." (PMID 38339275, 2024). "TIEG1 significantly inhibits the invasion of breast cancer cells, suppresses tumorigenesis in mice xenografts, and decreases metastasis to the lungs by inhibiting transcription of the EGFR gene and the EGFR signaling pathway." (PMID 38522013, 2024). "Our results collectively suggest that TRPV3 siRNA inhibits migration and proliferation, and promoted apoptosis in breast cancer cells by EGFR/AKT pathway." (PMID 38706904, 2024). "Research indicates that the EGFR plays a crucial role in the initiation, progression, and metastasis of primary breast cancer." (PMID 38751788, 2024).
breast carcinoma (continued). "An exemplary case is the EGFR gene, which exhibits frequent overexpression in basal breast cancer and contributes to the aggressive behavior of this subtype." (PMID 38213995, 2024). "In clinical cases of breast cancer, a significant association was found between GLUT1 expression and EGFR." (PMID 38831321, 2024). "Evidence suggests that miR-133a has the capability to inhibit the PAM pathway through its targeting of EGFR, thereby positioning it as a promising downstream target for suppressing cell proliferation in breast cancer." (PMID 38504785, 2024). "Positive staining for EGFR and P63 suggests that the tumor possesses the characteristics of basal-like breast carcinoma." (PMID 39058816, 2024). "Several proteins involved in this pathway are associated with breast cancer prognosis (including ERCC6 and POSTN34,35) and/or sensitivity/resistance to endocrine or other chemotherapy (including EGFR, ABL1, GNA13, and PTK736–39)." (PMID 39030258, 2024). "In this work, a congeneric set of quinoline-tethered cis-vinyl triamide hybrids was prepared and evaluated as EGFR tyrosine kinase inhibitors for the management of breast cancer." (PMID 39114435, 2024). "Lastly, SGCE stabilizes EGFR to promote breast cancer stem cells, offering new insights into overcoming the challenges associated with targeting EGFR in current clinical trials." (PMID 38300336, 2024). "EGFR recruits AP-1 via its cytoplasmic domain; thus, investigation into the relationship between endosomal AP-1 and EGFR in breast cancer cells is required in future." (PMID 38265632, 2024). "PTPN12 is a tumor suppressor, whose frequent loss in aggressive breast cancers activates HER2 and EGFR and accelerates breast carcinogenesis and metastasis." (PMID 38886396, 2024). "Previously, ADAMTS1 was reported to promote metastasis of murine breast cancer through activating EGFR by shedding HB-EGF and amphiregulin." (PMID 38263290, 2024). "In that context, we have demonstrated that the expression of CCL2, a cytokine that is responsible for tumor-associated macrophage recruitment, is induced by HER2 overexpression in EGFR+ breast cancer cells." (PMID 39791720, 2024). "It is upregulated in breast cancer, and portends poor prognosis as its contributes to EGFR-TKI resistance by phosphorylating the downstream c-RAF and PI3K p85." (PMID 38914812, 2024). "For example, activation of Src kinase in certain breast cancer cells leads to EGFR phosphorylation and downstream effects." (PMID 38924082, 2024). "Among other factors, the expression of VEGF and EGFR has been shown to play a role in therapeutic resistance against breast cancer treatment." (PMID 39405290, 2024). "Based on our examination of several cancer cell lines, it appears that the ability of TSL to induce methuosis is limited to ER+ and HER2+/EGFR+ breast cancer cells." (PMID 39906392, 2024). "For example, miR-338-3p has been identified as a downstream effector of EGFR overexpression in breast cancer." (PMID 39449799, 2024). "Our previous study has reported on the therapeutic role of HNPMI targeting EGFR and thus inferred it as a potential anti‐cancer agent against breast cancer." (PMID 37183661, 2024). "GALNT8‐mediated O‐Gal N Acylation suppresses the EGFR signaling pathway and metastatic potential in breast cancer cells." (PMID 38522013, 2024). "Overall, 2 patients experienced partial response, 1 with EGFR-amplified glioblastoma and 1 with multiple brain metastases from ERBB2-amplified and ERBB3-mutated breast cancer." (PMID 38680990, 2024). "Utilizing quantum dots in immunohistochemistry allowed for a more precise quantitative analysis of EGFR, aiming to determine its prognostic value in breast cancer." (PMID 38730959, 2024). "In the present research, the chemotherapeutic activity of TMZ on DMBA persuaded the breast cancer due to the modulation of EGFR/ERK/MMP-1 signaling way in rat model was exhibited." (PMID 38808816, 2024).
breast carcinoma (continued). "A recent study shows that the fungal metabolite cerulenin can target PKM2 via inhibiting EGFR 2 to downregulate the EMT in breast cancer cells." (PMID 39092293, 2024). "pNK cells were then co-cultured for 3 h at an E/T ratio of 20:1 with EGFR-expressing MDA-MB468 breast cancer cells in the absence or presence of increasing amounts of NKAB-EGFR." (PMID 38334638, 2024). "Breast cancer patients with elevated expression of PTGS2/ESR2/EGFR/JUN/MMP2 genes’ signature displayed significantly poor OS (P = 0.026) and DMFS (P = 0.0066) and consequently unfavorable prognosis." (PMID 39707884, 2024). "Higher expression of epidermal growth factor receptor (EGFR) in breast CSCs has been used as a molecular target for breast cancer therapeutics." (PMID 38522013, 2024). "Generally, studies have reported an overexpression of EGFR ranging from 16% to 36% in breast cancer cases." (PMID 39405290, 2024). "The question of its specificity raises intriguing possibilities about the involvement of signaling pathways or receptors uniquely dysregulated or overexpressed in ER+ and HER2+/EGFR+ breast cancer cells." (PMID 39906392, 2024). "NO signaling via the EGFR has been well-documented in breast cancer, with high levels of iNOS expression correlated with EGFR Y1173 phosphorylation in ER-negative patient samples." (PMID 38601214, 2024). "Lapatinib was the first HER2-targeting TKI approved for the treatment of HER2+ breast cancer and is a reversible dual inhibitor of epidermal growth factor receptor (EGFR) and HER2." (PMID 39191139, 2024). "One of the ways to fight BLBC (basal-like breast cancer) that causes brain metastasis (BM) is to target DR4/5 (death receptor) and EGFR antigens, which are overexpressed in BLBC." (PMID 38341580, 2024). "Anti-EGFR antibodies show limited response in breast cancer, partly due to activation of compensatory pathways." (PMID 38772416, 2024). "Then, we conducted assessments of mRNA and protein expression levels of hormone receptors (ER and PR), HER2, and EGFR in breast cancer cells using RT-qPCR and Western blot techniques." (PMID 38339428, 2024). "We found that SUSD2 levels were increased in an EGFR+ cell line overexpressing HER2 and that SUSD2 levels were associated with poor patient survival in HER2+ breast cancer." (PMID 39791720, 2024). "Activation of the EGFR is necessary for tumor survival and growth, especially in breast cancer and head and neck squamous cell carcinoma." (PMID 38543009, 2024). "The cholesterol biosynthesis enzyme MSMO1, a C4-methyl sterol oxidase in the Bloch pathway, has previously been shown to regulate EGFR signaling in breast cancer cells." (PMID 38488003, 2024). "Breast cancer often exhibits Epidermal Growth Factor Receptor (EGFR) overexpression, and studies have reported that TNBC patients also exhibit EGFR overexpression with a prevalence rate that varies depending on the patient cohort." (PMID 38762624, 2024). "Our results showed that SUSD2 expression had a negative correlation with the relapse-free survival of patients with EGFR+ HER2+ breast cancer when compared to EGFR+ breast cancer patients." (PMID 39791720, 2024). "Patients with EGFR+ HER2+ breast cancer exhibited significantly lower survival rates than those with EGFR+ breast cancer." (PMID 39791720, 2024). "To further validate the regulation of the EGFR/PI3K/AKT/GPX4 signalling axis by ORes in breast cancer cells, we performed Western blot analysis to assess the expression levels of key proteins in this pathway." (PMID 39881871, 2024). "As a result, co-targeting DR4/5 and EGFR in BLBC showed to be effective in treating brain metastasis in breast cancer." (PMID 38341580, 2024). "β3 Integrins have been linked with KRAS to promote fitness and survival of established pancreatic, lung, and breast carcinomas and can promote resistance to EGFR inhibitors." (PMID 38755258, 2024).